IL1B (interleukin 1 beta)
Diseases named in the same sentence as IL1B in open-access papers (continued):
Sharing a sentence is not in itself a finding about the gene and the disease.
glioblastoma (continued). "In this study, we found that IL-1β also inhibits IDO1 mRNA expression in the A172 glioblastoma, IMR-32 neuroblastoma, and T98G glioblastoma human brain cell lines and in primary human neurons." (PMID 31119110, 2019). "Heat shock protein, crystallin alpha B (CRYAB) has also been described to be released from glioblastoma multiforme (GBM) derived-exosomes in response to exposure to pro-inflammatory cytokines IL-1β and TNF-α, to exert an anti-apoptotic activity." (PMID 31555295, 2019). "Regarding IL-1b it has been described that this substance is released by glioblastoma cells both in vitro and in vivo." (PMID 30647842, 2018). "In this study, after LPS incubation with U87 glioblastoma cell, the pro-inflammatory cytokine TNFα, IL1β, and IL6 levels were elevated; the response was reversed by co-incubation of polysaccharide fractions in LPS." (PMID 29530027, 2018). "IL-1β is known to activate the expression of C/EBPδ in human glioblastoma-astrocytoma U373MG cells and is expressed abundantly in the injured spinal cord." (PMID 26510742, 2016). "In the present study, we used both U373 glioblastoma cells and fetal astrocytes in culture to examine the effect of IL-1β on miR21, miR146a, and miR155 expression." (PMID 25986346, 2015). "T98G glioblastoma cells were transfected with a plasmid encoding T-antigen and were treated with IL-2, Rantes, IFN-γ, IL-1β, IL-13 and MCP1 at 12, 24, and 36hrs post-transfection." (PMID 26061652, 2015). "Anand Iyer, et.al 2012 reported that miR-146a mimics can significantly reduce the mRNA expression levels of TRAF6, IRAK1 and IRAK2 protein levels in IL-1β stimulated human astrocytes and glioblastoma cell line." (PMID 25083878, 2014). "Our major aim was to investigate the potential effect of inflammatory molecules, such as IL-1β on Kir4.1 expression using both a glioblastoma cell line and human astrocytes in culture." (PMID 23270518, 2012). "We demonstrated that these glioblastoma cells were put into relatively cytokine "rich" environment produced by AT-MSC containing IL-1β, IL-1ra, IL-2, IL-4, IL-6, IL-8, TNF-α, IFN-γ, CCL5, CCL26, CXCL10, PDGF-bb." (PMID 20509882, 2010). "Recently, we have shown the power of neuroinflammation, i.e., the role of IL-1β and its downstream signaling cascade, in glioblastoma pathogenesis, demonstrating targeting IL-1β and its signaling cascade using an IL-1 Receptor Antagonist as a promising therapy." (PMID 40801649, 2025). "Moreover, in the serum of patients with glioblastoma (the most typical parenchymal brain tumor), it has been reported that there is a significant overexpression of IL-6, IL-1β, TNF-α, IL-10, VEGF, FGF-2, IL-8, IL-2, and GM-CSF." (PMID 37368708, 2023). "Thus, the proliferative activity of glioblastoma cells and the content of HIF-1α were higher in tolerant to hypoxia rats, but the mortality associated with the tumor process and IL-1β level in them were lower than in susceptible animals." (PMID 37542119, 2023). "Notably, several studies have shown that the proinflammatory cytokine IL1β is significantly elevated in the serum of glioblastoma (GBM) patients and serves as a potential serum marker for this type of disease." (PMID 36199426, 2022). "The IL-1β expression is significantly upregulated in glioblastoma and negatively correlated with the expression levels of KCNJ10, suggesting that KCNJ10 may promote inflammation in the TME." (PMID 36199579, 2022). "Additionally, IL-1β contributes to cancer cell stemness, invasiveness, and drug resistance in glioblastoma." (PMID 34603399, 2021). "In intracranial U87 xenografts, immunostaining revealed that bevacizumab-resistant glioblastoma showed an increased amount of TAMs and increased M2/M1 ratio, defined by M2 markers (Arg-1, TGF-β, MMP9) and M1 markers (NOS2, CXCL10, IL-1β), compared to bevacizumab-sensitive glioblastoma." (PMID 34209679, 2021).
glioblastoma (continued). "In addition, aminoguanidine treatment inhibited NO production and prevented IDO1 protein level reductions in all IFN-γ- and IL-1β-costimulated A172 glioblastoma, IMR-32 neuroblastoma, and T98G glioblastoma human brain cell lines." (PMID 31119110, 2019). "Interestingly, IL-1β stimulation in all tested brain cell lines (A172; glioblastoma, IMR-32; neuroblastoma, and T98G; glioblastoma) severely reduced IFN-γ-induced IDO1 mRNA expression levels in a manner similar to or greater than that of the liver cell lines." (PMID 31119110, 2019). "Thus, molecular relationship between HIF-1α and IL-1β has been reported in glioblastoma cells, where IL-1β decreased HIF-1α levels and promoted apoptosis." (PMID 28106131, 2017). "To address the question of whether IL-1β was involved in the modulation of Kir4.1 expression we used both human fetal astrocytes and the U373 glioblastoma cell line in culture." (PMID 23270518, 2012). "However, in U87 glioblastoma cells, 6HLN mainly exhibited cancer-stimulatory effects by increasing cell viability, enhancing migratory properties supported by vimentin overexpression, and upregulating the expression of the IL1β proinflammatory protein." (PMID 39683752, 2024). "Therefore, targeting the production and activity of IL-1β might control the progression of glioblastoma." (PMID 35368876, 2022). "Moreover, pro-IL-1β and mature IL-1β protein levels simultaneously increased in glioblastoma cells." (PMID 34987700, 2021). "In particular, in the tumor microenvironment (TME) of glioblastomas (GBM), IL-1β is extensively abundant." (PMID 32069807, 2020). "IHC validation demonstrated increased expression of the M1 markers iNOS, IL-1β, as well as the M2 marker CD163, in SAMD9high glioblastoma tissues relative to SAMD9low tissues." (PMID 41331572, 2025). "After the shKDELC2 transfection of the glioblastoma cells, there was a significant decrease in NLRP3, caspase-1, and IL-1β expression compared to the shLuc-transfected GBM8401 and U87 cells." (PMID 37107298, 2023). "Their data showed that miR-93 was downregulated in human glioblastoma cell lines, and restoration of miR-93 levels in glioblastoma cells led to a decreased expression of an array of inflammatory genes (HIF-1α, MAP3K2, IL-6, G-CSF, IL-8, LIF, and IL-1β)." (PMID 38239396, 2023). "The concentrations of IL-1β, IL-6, IL-8, IL-10, TNFα, and HMGB1 confirmed that inflammation was a critical component of glioblastoma progression." (PMID 38003396, 2023). "IF was performed to observe the co-localization of the IL-1β and IL-18 pro-inflammatory cytokines with the GFAP glioblastoma marker." (PMID 35042538, 2022). "A high level of IL-1β was observed in glioblastoma cells (CCF3 and U87MG cells) and human glioblastoma specimens." (PMID 35368876, 2022). "Of note, in a mouse model of glioblastoma, CX3CR1 deficiency led to increased CNS infiltration of CCR2+ monocytes into the tumor tissue, and it was suggested that this could be linked to increased microglial IL-1β, which in turn could induce CCL2 by tumor cells." (PMID 28320442, 2017). "Glioblastoma IL-1β processing occurred by the NLRP3 inflammasome, and ATP and nigericin increased IL-1β processing by upregulating NLRP3 expression, similar to macrophages." (PMID 25054228, 2014). "However, low expression levels of miR-329 correlate with survival in glioblastoma multiforme patients, studies of hippocampal neurons suggest it to be involved in dendritic outgrowth, and miR-329 expression is decreased in airway smooth muscle treated with IL-1β, TNFα, and IFNγ." (PMID 24143215, 2013). "Ketamine has also demonstrated anti-inflammatory potential in vitro, where it was observed to inhibit the production and release of pro-inflammatory cytokines, such as IL-6, IL-1β and TNF-α, in murine macrophages, primary rat microglial cells and human-derived glioblastoma cells." (PMID 40498007, 2025).
glioblastoma (continued). "CED of these recombinant cytokines in immunocompetent glioblastoma C57BL/6J mice nominated APOA1, IL-1B, and CCL4 as candidates that could increase immune cell infiltration and necrosis in the intracranial TIME." (PMID 40161763, 2025). "It has been reported that combined stimulation of IL-1β, IL-6, and IFN-γ in U373 glioblastoma cell lines and primary human astrocytes could induce APP production and lead to increased Aβ levels." (PMID 39626951, 2024). "Our research has observed changes in VCAM-1 expression in response to GBM spheroids and U-87 MG glioblastoma cells to G721–0282 treatment, mainly at concentrations of 100–25 μM, which could be explained by VCAM-1/IL-1β dependence." (PMID 39399677, 2024). "No significant alteration on the concentration of TNF-α and IL-1β in the culture medium of mNPCs with/without glioblastoma-derived EVs treatment was detected using ELISA." (PMID 35022057, 2022). "IL-1β silencing, however, did not increase the phosphorylated IκBα levels in RSL3-treated glioblastoma cells, implying that IL-1β expression is regulated by the NF-κB pathway, the activation of which is independent of IL-1β." (PMID 34987700, 2021). "Moreover, pericytes associated with glioblastoma multiforme (GBM) fatal brain tumors, contribute to the immune-suppressive micro-environment of this cancer by reduced expression of ICAM1 in response to pro-inflammatory cytokine IL-1β." (PMID 34408980, 2021). "Analysis of various human cell lines revealed that IL-1β-induced iNOS-dependent reduction of IDO1 mRNA expression occurred in brain cell lines (A172; glioblastoma, IMR-32; neuroblastoma, and T98G; glioblastoma) and liver cell lines (Huh7 and HepG2), but not in other cell lines." (PMID 31119110, 2019). "Moreover, IL-1β induces RUNX1 expression through the MAPK signalling pathway and promotes migration, invasion, and angiogenesis in glioblastoma." (PMID 31592165, 2019). "In previous experiments with human glioblastoma cells and alveolar epithelial cells, we found that TNFα and IL-1β, respectively, did not induce IDO1 directly, but required IFN-γ to synergistically induce IDO1." (PMID 31267172, 2019). "We also noticed that the transcription of key genes involved in inflammation, proliferation, angiogenesis and extracellular matrix remodelling (including MMP2, HIF1A, IL1B, IL1A, IL1R1, MMP2, VEGFA), processes vital to glioblastoma development, were down-regulated by RND3 knock-down." (PMID 26132659, 2015). "In both the glioblastoma cell line and human astrocytes transfection with miR-146a mimic, significantly reduced IRAK-1, IRAK-2 and TRAF-6 mRNA and IRAK-1 protein after stimulation with IL-1β." (PMID 23028621, 2012). "Molecular markers of glioblastoma such as methylated O6-methylguanine-DNA methyltransferase (MGMT) promoter methylation was seen in 16 out of the 33 patients evaluated (48%) and expression of immunological markers such as TNF-a, IL-1β, and IL-6 was considered in one patient." (PMID 38137175, 2023). "Interestingly, in human glioblastoma and fibrosarcoma cell lines, IL-1β was shown to induce phosphorylation of STAT1Ser727 but not STAT1Tyr701, which had a synergistic effect on IFN-γ-induced gene expression." (PMID 32341343, 2020). "However, the spheroids formed by TRAF3IP2-silenced U87 cells (U87TRAF3IP2KDversus U87control shRNA cells) expressed markedly reduced VEGF, IL-17R, IL-1β, IL-6, and IL-8 expression, further demonstrating a pro-angiogenic and pro-inflammatory role of TRAF3IP2 in glioblastoma cells." (PMID 30038719, 2018). "Our research has shown decreasing in VCAM-1 expression in GBM spheroids and also in U-87 MG glioblastoma cells to G721-0282 treatment, mainly at concentrations of 100 − 25 μM, which could be explained by VCAM-1/IL-1β dependence." (PMID 39607670, 2025).
glioblastoma (continued). "To examine whether IL-1β-induced iNOS expression and NO production are involved in proparasitic functions in A172 glioblastoma, IMR-32 neuroblastoma, and T98G glioblastoma cells, we compared the IFN-γ-mediated reduction of T. gondii numbers in the presence or absence of IL-1β." (PMID 31119110, 2019).
Allergy (72 papers, 2010 to 2025). An allergy is an immune response or reaction to substances that are usually not harmful. "It was found that HMGB1, HMGB2, IL-6, IL-1β, and family history of allergy were the risk factors for AR." (PMID 37713866, 2023). "The association between allergic diseases and poor oral health is related to increased levels of inflammatory cytokines, such as interleukin (IL)-1β, IL-6, and tumor necrosis factor-α." (PMID 36833618, 2023). "Some studies suggest that insufficient sleep can alter levels of inflammatory cytokines such as interleukin (IL)-1β, IL-4, IL-6, and IL-10, which may promote allergic reactions and elevate the risk of developing AR." (PMID 40283018, 2025). "Nevertheless, to the author’s knowledge, this is the first piece of work that establishes a connection between TGF-β/Smad pathway, IL-1β and IL-6 levels, metabolic pathways, the type of allergy, metabolic dysregulations, and the risk of cancer within a unified framework." (PMID 38629073, 2024). "Finally, we found that HMGB1, HMGB2, IL-6, IL-1β, and family history of allergy were the risk factors for AR." (PMID 37713866, 2023). "The high production of fecal EDN, IL-1β, and IL-10 during the first weeks of life may therefore be an indicator for later risk of allergic diseases." (PMID 35628877, 2022). "Furthermore, we examined specific SNPs in the TSLP and IL-1β genes to determine their association with the occurrence and number of coexisting allergic diseases, addressing the gaps in understanding the genetic and immunological mechanisms underlying allergic multimorbidity." (PMID 39860604, 2025). "Allergy symptom scoring (gastrointestinal, respiratory, skin, and systemic allergy reflections); inflammatory factors (TNFα/IL-1β/IL-6/IL-10); antibodies (IgE/IgG2); efficacy in eczema reduction." (PMID 40529417, 2025). "In the allergy group, IL-1β levels were 5.5 times higher than in the control group, with a mean concentration of 337 pg/mL compared to 62 pg/mL in controls." (PMID 39860604, 2025). "Proinflammatory cytokines with high importance in developing allergic reactions: IL-1β, IL-6, TNF-α, TGF-β, and GM-CSF were selected for the study." (PMID 39881795, 2025). "For instance, recently the pro-inflammatory IL-1β was demonstrated to be of great importance in the development of allergic diseases." (PMID 40507979, 2025). "Elevated levels of IL-1β have been observed in various allergic diseases, where it contributes to tissue damage, chronicity, and exacerbations." (PMID 39860604, 2025). "At the same time, IL-1β, IL-4, and IL-17 levels were reduced, demonstrating the immunosuppressive nature of cancer patients and a lower occurrence of allergies." (PMID 38951583, 2024). "This is interesting as an in vitro study has shown that synthesis of lactose in lactating mammary epithelial cells is inhibited by pro-inflammatory cytokines TNF-α, IL-1β and IL-6, all of which play roles in allergy." (PMID 39458508, 2024). "Although conducted in BALB/c mice, it has been shown that functional IL-1β signaling via NLRP3 is required in an ovalbumin-induced model of allergy." (PMID 38933263, 2024). "Recently, accumulating evidence from human and mouse experiments has demonstrated the critical involvement of the NLRP3 inflammasome, IL-1β, and IL-18 in the development of allergic diseases." (PMID 38277371, 2024). "OLT1177’s specific inhibition of NLRP3 inflammasomes offers a promising therapeutic approach to prevent the release of pro-inflammatory factors IL-1β and IL-18, potentially benefiting the treatment of allergic diseases." (PMID 39131161, 2024). "Recent studies in humans and mice strongly suggest a link between the NLRP3 inflammasome, IL-1β, and IL-18, and the development of allergic diseases." (PMID 39131161, 2024). "It operates by inhibiting the activities of NLRP3, caspase-1, and ASC, thereby reducing the secretion of IL-1β and IL-18 in various allergic diseases." (PMID 39131161, 2024).
Allergy (continued). "IL-13 is a Th2 cytokine in the immune system thought to play an important role in the development of allergies, although it has also been ascribed anti-inflammatory roles, inhibiting different pro-inflammatory mediators such as IL-1β and TNF-α." (PMID 37373554, 2023). "In conclusion, IL-1β is closely related to the occurrence and development of AR, with shared and unique roles when compared with other allergic diseases." (PMID 37091903, 2023). "Interventions (e.g., IL-1β receptor antagonists (IL-1Ra) and IL-1β inhibitors) on the IL-1β signaling system have also become research hotspots in the treatment of allergic diseases." (PMID 37091903, 2023). "Interleukin-1β (IL-1β), one of the core factors in the occurrence and development of inflammation, plays a key role in allergic diseases." (PMID 37091903, 2023). "Previous studies have shown that interleukin-1β (IL-1β) acts as a key cytokine to participate in and promote the occurrence and development of allergic diseases." (PMID 37091903, 2023). "IL-1β, as a key cytokine in the development of inflammation, has also been found to play an important role in allergic diseases such as AR, allergic asthma, and atopic dermatitis." (PMID 37091903, 2023). "This article systematically summarizes the research advances in the roles of IL-1β in allergic diseases, focusing on the changes of IL-1β in AR and the possible interventions." (PMID 37091903, 2023). "IL-1β and IL-18 can stimulate the differentiation and proliferation of Th2 cells and exacerbate related allergic reactions." (PMID 37817225, 2023). "Although the ultimate effector site of the disease varies, the effects of IL-1β have been reported to be closely related to eosinophilia, IgE switching, and Th2 inflammation in allergic diseases." (PMID 37091903, 2023). "IFN-γ and IL-1β, which were significantly decreased in the allergy group, increased significantly after SI treatment (p < 0.05)." (PMID 36359214, 2022). "In the allergy group, the circulating concentration of interleukin 1 beta had significantly increased (p < 0.05) compared to that in the control group." (PMID 35805534, 2022). "In turn, among patients with delayed-type hypersensitivity, the level of interleukin 1 beta was significantly (p < 0,05) higher when compared to the control group and significantly (p < 0.05) lower in comparison with IgE-mediated allergy patients." (PMID 35805534, 2022). "IL‐1β is produced principally from monocytes and macrophages and contributes to allergic disease by promoting mast cell activation and T2 cytokine production." (PMID 35988262, 2022). "Although infection is the primary cause of fever, endogenous heat sources such as IL-1β, TNF, IL-6, and PTGS2-induced prostaglandins also act on the thermoregulatory centers of allergic diseases." (PMID 35855823, 2022). "An increase in regulatory cytokine IL-2 and TGF-β was detected, as was the reduction of IL-4, IL-17, and IL-1β, reflecting the cancer patient's immunosuppressive environment and the lower prevalence of allergies." (PMID 34518597, 2021). "PMA/A23187 acts on mast cells and induces them to produce IL-1β, IL-6, TSLP, and TNF-α, causing allergy-related inflammation." (PMID 34681651, 2021). "IL-1β is the main secretory subtype of IL-1, which can mediate the development of allergic diseases and asthma via differentiation and activation of Th2 cells and Th17 cells." (PMID 33503170, 2021). "Intrathecal injection of the IL-1β specific antibody can prevent pain allergic reaction induced by MMP-9, indicating that IL-1β is involved in the development of NP." (PMID 34572554, 2021). "IL-1β exacerbates autoimmune and allergic diseases including atopic dermatitis, contact hypersensitivity, and bronchial asthma." (PMID 32063904, 2020). "While histamine significantly induced IL-1β concentration in the allergy group compared to PBMCs incubated in pure medium, osthole significantly decreased the amount of interleukin." (PMID 30620999, 2019).